NAP1L1 (nucleosome assembly protein 1 like 1)
Diseases named in the same sentence as NAP1L1 in open-access papers (continued):
Sharing a sentence is not in itself a finding about the gene and the disease.
ischemic cardiomyopathy (2 papers, 2023 to 2025). Ischemic cardiomyopathy is a cardiomyopathy in which a weakness in the muscle of the heart due to inadequate oxygen delivery to the myocardium with coronary artery disease being the most common cause. "Here, we report that NAP1L1 is a significant regulator of cardiac fibrosis and is upregulated in ischemic cardiomyopathy patient hearts." (PMID 37593048, 2023). "In ischemic cardiomyopathy (ICM) patients' hearts and myocardial fibrosis after MI, we detected higher expression of NAP1L1." (PMID 37593048, 2023).
lung carcinoma (2 papers, 2018 to 2022). "Other NETest markers involved in growth factor signaling and genes involved in the regulation of the neuroendocrine phenotype e.g., cell secretion and granule transport, or other canonical neuroendocrine marker genes, e.g., TPH1 and NAP1L1 were also scarcely detectable in lung cancers." (PMID 29467960, 2018).
Myocardial fibrosis (2 papers, 2023 to 2025). "Nap1l1 p.D349E KI mice also showed more severe myocardial fibrosis Nap1l1 p.D349E KI mice exhibited worse cardiac function, including LVPW;d, LVPW;s, EF, FS." (PMID 40169585, 2025). "In addition to increased size, cardiomyocytes from NAP1L1 p.D349E AAV-treated mice showed more severe myocardial fibrosis." (PMID 40169585, 2025). "NAP1L1 was identified for the first time in this study as a mediator of myocardial fibrosis." (PMID 37593048, 2023). "Taken together, NAP1L1 is a master‐induced factor of fibroblast activation and myocardial fibrosis, which could be a potential hub for targeting the treatment of the disease." (PMID 37593048, 2023). "Collectively, NAP1L1 could potentially be a new therapeutic target for various cardiac disorders, including myocardial fibrosis." (PMID 37593048, 2023). "Nucleosome assembly protein 1 like 1 (NAP1L1), which was the dysregulated hub protein in myocardial fibrosis post‐myocardial infarction." (PMID 37593048, 2023). "More importantly, knockdown NAP1L1 restored cardiac function post‐myocardial infarction (MI) and inhibited excessive deposition of ECM, and blocked the fibroblast‐to‐myofibroblast trans‐differentiation process, indicating that it can be a potential treatment target for myocardial fibrosis." (PMID 37593048, 2023).
pancreatic neuroendocrine tumor (2 papers, 2018 to 2022). Pancreatic endocrine tumor, also known as pancreatic neuroendocrine tumor (PNET), describes a group of endocrine tumors originating in the pancreas that are usually indolent and benign, but may have the potential to be malignant. "Additionally, enhancement of NAP1L1 is found in pancreatic neuroendocrine tumor metastasis, expediting methylation by controlling p57 (Kip2) for motivated cell proliferation." (PMID 34898380, 2022). "It was interesting that NAP1L1 affected the proliferation of pancreatic neuroendocrine tumor cells via modulation of p57 (Kip2) promoter methylation, whether affected insulin secretion or regulated blood glucose, however, the mechanism had not been elucidated." (PMID 30299268, 2018).
Sepsis (2 papers, 2022 to 2024). Sepsis is defined as life-threatening organ dysfunction caused by a dysregulated host response to infection. "Nevertheless, our results support the conclusion of differential functions of NAP1L1 in MKs and PLTs during systemic inflammation and open a new avenue of sepsis research focused on the MK-PLT axis." (PMID 36499021, 2022). "Because of its clinical relevance, we decided to study NAP1L1 expression and potential function in a common, morbid, and often fatal systemic inflammatory disease—sepsis." (PMID 36499021, 2022). "To determine whether transcripts coding for NAP1L1 were altered in PLTs during sepsis, we used RNA-seq on highly purified PLTs from septic patients and matched healthy donors." (PMID 36499021, 2022). "Having detected significantly increased NAP1L1 transcript levels in PLTs from septic patients, we hypothesized that NAP1L1 protein expression would similarly be altered during sepsis." (PMID 36499021, 2022). "Our single-cell sequencing data demonstrated that sepsis marker genes were highly elevated in CD16+ monocytes, including NAP1L1, CFD, BID, BCL2A1, MALAT1, RNH1, and LILRA5 genes." (PMID 39294473, 2024).
small intestinal neuroendocrine neoplasms (2 papers, 2014 to 2020). "The chromatin remodeler NAP1L1, which is upregulated in small intestinal neuroendocrine neoplasms (NENs), has been implicated in cell cycle progression." (PMID 25071868, 2014).
Goblet cell carcinoids (1 paper, 2009). "Goblet cell carcinoids have increased expression of NAP1L1, MAGE-D2, and MTA-1 genes compared with benign carcinoids." (PMID 19171048, 2009).
Hyperglycemia (1 paper, 2022). An increased concentration of glucose in the blood. "In summary, hyperglycemia-induced Pin1/BRD4 axis promoted gastric tumorigenicity and tumor metastasis by facilitating NAP1L1 and repressing P21 in vivo." (PMID 35461311, 2022).
Hypertension (1 paper, 2025). The presence of chronic increased pressure in the systemic arterial system. "This hypothesis is supported by clinical observations that patients carrying the NAP1L1 p.D349E, despite lacking hypertension or other abnormal loading conditions, present with hypertrophic changes." (PMID 40169585, 2025).
hypertrophic cardiomyopathy (1 paper, 2025). A condition in which the myocardium is hypertrophied without an obvious cause. "Here, the authors identify a mutation in the gene NAP1L1 to be associated with cases of hypertrophic cardiomyopathy, linking it to cGAS-STING-IFN signaling." (PMID 40169585, 2025). "Given that fibrosis is a common feature in both ischemic and hypertrophic cardiomyopathy, the interaction of NAP1L1 with pathways regulating cardiac remodeling, such as YAP1, may be relevant." (PMID 40169585, 2025).
liver cancer (1 paper, 2019). An epithelial or non-epithelial malignant neoplasm that arises from the liver. "Meanwhile, the direct target gene of NOTCH1, ABCG2 were also decreased in liver cancer cells which was down-regulated NAP1L1 expression." (PMID 31516385, 2019). "Moreover, NOTCH1 and ABCG2 protein expression levels were decreased concurrent with NAP1L1 down-regulation in liver cancer cells by WB analysis." (PMID 31516385, 2019).
lymphoma (1 paper, 2008). A malignant (clonal) proliferation of B- lymphocytes or T- lymphocytes which involves the lymph nodes, bone marrow and/or extranodal sites. "Genes whose expression was “high” in more than 95% of human lymphomas, whose gene names include: BZW2, H2AFY, SFRS3, NAP1L1, NOLA2, UBE2D2 and CCNG1 (p = 4.07×10−5)." (PMID 18535662, 2008).
melanoma (1 paper, 2014). A malignant, usually aggressive tumor composed of atypical, neoplastic melanocytes. "For example PPIP5K1->CATSPER2 and YARS2->NAP1L1 have been predicted in melanoma samples." (PMID 25133550, 2014).
neuroblastoma (1 paper, 2010). Neuroblastoma (NB) is the most common solid, extracranial childhood tumor. "Notably, we compared the presence of the specific cassette exons in RNA from normal brain and neuroblastoma (for ATP6v0A1, STRADA, PCNP and CS) and from skeletal muscle and rhabdomyosarcoma (for TPM3, TPD52L2, NAP1L1, METT10 D and SLC25A3)." (PMID 20813049, 2010).
pancreatic (1 paper, 2014). "In 43 pancreatic NEN samples (38 primaries and 5 metastasis), NAP1L1 was over-expressed in metastasis (p < 0.001), expression which was inversely correlated with p57Kip2 (p < 0.01) on mRNA and protein levels." (PMID 25071868, 2014).
rhabdomyosarcoma (1 paper, 2010). A rare aggressive malignant mesenchymal neoplasm arising from skeletal muscle. "We observed that NAP1L1 transcripts including these cassette exons are expressed in both normal and tumoral conditions, but they are much more expressed in rhabdomyosarcoma respect to normal skeletal muscle tissue (about 5-fold)." (PMID 20813049, 2010).
salivary gland neoplasm (1 paper, 2025). Tumors of the SALIVARY GLANDS. "In this article, we describe a unique case of CASG arising in the sinonasal cavity of a 49-year-old female, with a novel NAP1L1::PRKD1 fusion, expanding the molecular complexities of salivary gland neoplasms." (PMID 41357817, 2025).
tumor (26 papers, 2008 to 2026). "Furthermore, multivariate analyses revealed that NAP1L1 expression in tumor cells was an independent and significant risk factor affecting patients’ overall survival and disease-free survival after curative resection." (PMID 31516385, 2019). "We hypothesize that TIA-1 plays a fundamental role in the post-transcriptional regulation of NAP1L1 and that alteration of this regulatory process contributes to NAP1L1-associated tumor development." (PMID 24401680, 2014). "Mapping tumor subpopulations onto this trajectory revealed that C0 NAP1L1+ TCs and C2 MKI67+ TCs generally occupied the early pseudotime segment, C3 ITLN1+ TCs were situated in the intermediate region, and C1 CA2+ TCs were primarily found in the late segment." (PMID 40842994, 2025). "We classified a total of 7,759 tumor cells into separate subpopulations based on their DEGs and designated each cluster according to its most prominently expressed marker gene: C0 NAP1L1+ TCs, C1 CA2+ TCs, C2 MKI67+ TCs, and C3 ITLN1+ TCs." (PMID 40842994, 2025). "C0 NAP1L1+ TCs comprised the predominant fraction and were significantly represented across all five tumor stages." (PMID 40842994, 2025). "In HCC, NAP1L1 has also been proven to facilitate tumor progression by activating multiple different signaling pathways." (PMID 38816735, 2024). "Previous studies have demonstrated that knockdown of NAP1L1 depolarises the mitochondrial membrane potential, which in turn mediates tumour cell apoptosis." (PMID 38538582, 2024). "High NAP1L1 expression in HCC tissues is associated with aggressive clinicopathologic features, such as high serum AFP levels, tumor size, and tumor number." (PMID 36980210, 2023). "The mechanistic experiments showed that the binding of MYH9 to NAP1L1, a potential promoter of tumor proliferation, inhibited the ubiquitination and degradation of NAP1L1 by recruiting USP14." (PMID 37770914, 2023). "Huaier/let-7d-5p/NAP1L1 axis is supposed to be a promising target for the treatment of angiogenesis and tumor growth in LC via elevated let-7d-5p and targeted NAP1L1." (PMID 34898380, 2022). "From those scatterplots, we concluded that the NAP1L1 expression of HCC specimens was evidently higher than that of the non-tumor specimens (p < 0.05)." (PMID 35664324, 2022). "Gene expression analyses using the ONCOMINE and the TIMER claimed that NAP1L1 mRNA levels were evidently higher in HCC than in non-tumor tissues." (PMID 35664324, 2022). "In brief, Huaier restrains angiogenesis and tumor growth in LC via motivating let-7d-5p and targeted NAP1L1." (PMID 34898380, 2022). "It is recommended that more studies are supposed to be conducted to verify the function of the Huaier/let-7d-5p/NAP1L1 axis in LC angiogenesis and tumor growth." (PMID 34898380, 2022). "The study was to explore the potential mechanism of Huaier repressing angiogenesis and tumor growth in LC via strengthening let-7d-5p and targeting NAP1L1." (PMID 34898380, 2022). "Inspired via these explorations, this study was used to explore the repression of angiogenesis and tumor growth in LC via elevated let-7d-5p and targeting NAP1L1 via Huaier." (PMID 34898380, 2022). "The data indicate that NAP1L1 is a tumor promoter, significantly involved in the pathogenesis of HCC." (PMID 34368121, 2021). "Recent studies on HCC showed that PRDM8 suppresses the occurrence of tumor via interacting with NAP1L1." (PMID 34368121, 2021). "Several previous studies show that NAP1L1 expression is strictly correlated with malignant neoplastic progression in several tumor types." (PMID 34959221, 2021). "In previous studies, NAP1L1 has been reported to be involved in promoting tumor pathogenesis, but few studies have shown its role in cancers." (PMID 34368121, 2021). "These mechanistic studies demonstrated that NAP1L1 as a tumor promoter participated in tumor pathogenesis." (PMID 34774047, 2021).
tumor (continued). "In this study, NAP1L1 protein was upregulated based on the Clinical Proteomic Tumor Analysis Consortium (CPTAC) database." (PMID 34774047, 2021). "Thus reduced NAP1L1 protein expression could be mechanistically associated with tumor progression." (PMID 32850460, 2020). "Following confirmation of our findings, we investigated the mRNA and protein expression of NAP1L1 in tumor and adjacent normal mucosa samples from patients with CRC as well as colonic tissues from unaffected individuals." (PMID 32850460, 2020). "Results showed that the NAP1L1 expression levels in the tumor cell cytoplasm varied widely among different HCC specimens." (PMID 31516385, 2019). "Of the 219 patients at stage I–II, 86 patients were identified as having positive NAP1L1 expression in tumor cells." (PMID 31516385, 2019). "Based on NAP1L1 expression in the tumor cell cytoplasm, patients were divided into two groups, the NAP1L1 low group (NAP1L1-Lo) and the NAP1L1 high group (NAP1L1-Hi)." (PMID 31516385, 2019). "IHC analysis in the excised tumor sections demonstrated that Ki67-positive cells were decreased, while cleaved caspase 3-positive cells were increased in the sk-hep-1-sh-NAP1L1 plus DOX group compared with that of either agent alone." (PMID 31516385, 2019). "High NAP1L1 expression was significantly associated with aggressive clinicopathologic features (i.e., serum AFP levels, larger tumor size, and late clinical stage)." (PMID 31516385, 2019). "High NAP1L1 expression in HCC tissues was associated with aggressive clinicopathologic features, such as serum AFP levels, tumor size and tumor number." (PMID 31516385, 2019). "We next analyzed the relationship between NAP1L1 expression levels in tumor cells and the clinicopathological characteristics." (PMID 31516385, 2019). "We considered that p57Kip2, as a tumor suppressor, would be silenced in proliferating/neoplastic neuroendocrine cells as a consequence of NAP1L1 activity." (PMID 25071868, 2014). "Based on this mechanism, suppression of NAP1L1 may inhibit tumour progression in patients with HCC with high protein expression of NAP1L1 or BIRC2." (PMID 38538582, 2024). "Tumour progression may be inhibited by suppressing NAP1L1 expression in patients with HCC with high protein expression of NAP1L1 and BIRC2." (PMID 38538582, 2024). "Although NAP1L1 can induce the apoptotic escape of tumour cells, whether it determines the progression of HCC by affecting the stability of BIRC2, a key factor in apoptotic escape, remains unclear." (PMID 38538582, 2024). "Nucleosome assembly protein 1-like 1 (NAP1L1) is highly expressed in various types of cancer and plays an important role in carcinogenesis, but its specific role in tumor development and progression remains largely unknown." (PMID 35351053, 2022). "Huaier restrained angiogenesis and tumor growth of LC in vivo and in vitro; Augmented let-7d-5p or declined NAP1L1 motivated the therapy of Huaier on LC; Let-7d-5p negatively modulated NAP1L1; Elevated NAP1L1 reversed the influence of enhancive let-7d-5p." (PMID 34898380, 2022). "NAP1L1 may contribute to the aggressive nature of tumor cells through the PI3K/AKT/mTOR signaling pathway in lung AC." (PMID 35351053, 2022). "We found that tumor T-effector scores were positively correlated with NAP1L1 levels." (PMID 35440542, 2022). "Moreover, the mice injected with shNAP1L1-U87 and shNAP1L1-LN229 cells exhibited lower expressions of Ki67, proliferating cell nuclear antigen (PCNA) and NAP1L1 in tumor tissues relative to the control mice." (PMID 34959221, 2021). "In HCC, NAP1L1 acts as a tumor promoter and is repressed by PRDM8 and let-7c-5p." (PMID 34368121, 2021). "In addition, NAP1L1 knockdown attenuates p65 binding to the antiapoptotic Mcl-1 gene promoter and reduces its expression, which finally induced cell apoptosis in tumor cells." (PMID 34774047, 2021). "In previous studies, NAP1L1 is reported to correlate with tumor pathogenesis." (PMID 34774047, 2021).